LGALS3 (galectin 3)
Diseases named in the same sentence as LGALS3 in open-access papers (continued):
Sharing a sentence is not in itself a finding about the gene and the disease.
cancer (continued). "Cav1 gene expression has been observed to coordinate with Lgals3 in several cancers, and their encoded proteins together have been seen to regulate the downstream pathway signaling." (PMID 29084770, 2017). "Another finding establishing a correlation between MVMp uptake and cancer cells is the requirement of MVMp for galectin-3, a multifunctional protein implicated in cancer metastasis." (PMID 29072600, 2017). "The most studied member of the galectin family, galectin-3 is known to be associated with cancer aggressiveness and metastasis." (PMID 28678156, 2017). "This suggests that LSD1 is rather implicated in cancer stem cell function by regulating galectin-3-integrin β3-KRAS signaling." (PMID 28860622, 2017). "Galectin-3 was first associated with Ras signaling in cancers, as galectin-3 interacts selectively through its CRD with activated K-Ras (K-Ras-GTP) and stabilizes it in the “on” state." (PMID 27242966, 2016). "Interaction of cancer-associated TF with endothelium-associated galectin-3 showed to affect initial stages of cancer cell–endothelium adhesion." (PMID 27066458, 2016). "Together, these results indicate that the heparin derivatives also inhibit cell adhesion mediated by cancer cell-associated galectin-3." (PMID 26160844, 2015). "Cancer-associated isoforms of MMP-9 bound galectin-3 in a rather reduced manner than natural MMP-9 did." (PMID 26528431, 2015). "Subsequent to its identification in 1989 as Mac-2, a galactose-binding lectin and macrophage marker, Galectin-3 has been implicated in a wide spectrum of pathological conditions including cancer and inflammation." (PMID 25869099, 2015). "There is accumulating evidence that the cancer-associated T, Tn, and sTn structures promote metastasis through binding to Galectin-3." (PMID 24592356, 2014). "Galectin-3 expression is also increased in patient sera of several cancer types and associated with increased risk of metastasis." (PMID 24592356, 2014). "Numerous mechanisms underlie cancer chemoresistance, but it appears that galectin-3 which is overexpressed in numerous tumor types, suppresses cell apoptosis and hence, decreases sensitivity of cancer cells to chemotherapeutic drugs." (PMID 24115933, 2013). "Increased galectin-3 levels have been associated with various diseases, including cancer, immunological disorders, and cardiovascular traits." (PMID 23056639, 2012). "Exposure of MDA-MB-231 cells to D609 also resulted in decreased galectin-3, a protein implicated in cancer cell growth, adhesion, angiogenesis, and metastatic potential." (PMID 22429397, 2012). "Increased circulating levels of galectin-3 have been associated with various diseases, including cancer, immunological disorders, and cardiovascular disease." (PMID 23056639, 2012). "Galectin-3 (Gal-3), a 31 kDa member of the family of beta-galactoside-binding proteins, has been implicated in the progression of different human cancers." (PMID 21698183, 2011). "Gal-3C has previously shown anticancer activity in a mouse model of metastatic breast cancer, and is thought to act through inhibition of functionality of galectin-3 which has been strongly implicated in the progression of cancer." (PMID 21765917, 2011). "The expression of the anti-apoptotic molecule galectin-3 is restricted to cancer cells and this feature has potential diagnostic and therapeutic implications." (PMID 19020658, 2008). "In several experimental systems galectin-3 expression in cancer cells was associated with a metastatic phenotype." (PMID 19055814, 2008). "Many cell surface molecules and basement matrix proteins e.g. growth factor receptors, adhesion molecules and death receptors, have been reported to carry galactose-terminated N- or O-linked glycans and are involved in galectin-3-mediated cancer promotion and immune cell activities." (PMID 41023585, 2025).
cancer (continued). "Interestingly, single nucleotide polymorphisms (SNPs) within the gal-3 coding gene (LGALS3) have been associated with cancer risk, adding further evidence to the studies suggesting the carcinogenic roles of this protein." (PMID 38933925, 2024). "In addition, abnormal galectin-3 expression is known to be associated with cancer initiation, progression, and metastasis." (PMID 38195853, 2024). "Notably, Lgals3 (encoding galectin-3) is an exception as it is further up-regulated in the cancer plasmids-TAA groups, is up-regulated in a different plasmid-HTVI-injury model and is associated with poorer prognosis in HCC." (PMID 39254423, 2024). "LGALS3 has been linked to poor prognosis in EOC80 with the assertion that it may be activating the Wnt/β-Catenin pathway to effect cancer stemness mechanisms." (PMID 38086828, 2023). "Moreover, galectin-3 is engaged in the regulation of main cytokines involved in inflammation, inducing those that have been implicated in cancer, such as interleukin-6." (PMID 37345016, 2023). "High levels of galectin-3 cause endocytosis of integrins resulting in cytoskeletal reorganization, such that the cell adhesions tend to be loose and cause dissemination of the cancer cells." (PMID 37444377, 2023). "The extraction of these ion transport proteins by galectin-3 indicates that they carry O-linked glycans and their interaction with galectin-3 may influence ion/molecular transportation cross the cell membrane during cancer development." (PMID 37612278, 2023). "Previous studies have also indicated galectin-3 as a diagnostic or prognostic biomarker in monitoring disease progression or response to therapy in certain types of heart disease, kidney disease and cancer." (PMID 36914828, 2023). "In addition to cell mobility and invasion, galectin-3 displayed an association with chronic inflammation, enhancing the fibrotic pathogenesis in many types of tissues and cancers." (PMID 36713574, 2022). "Galectin 3 (encoded by LGALS3) promotes the interaction between cancer and stromal cells through the secretion of proinflammatory cytokines and the activation of integrin signaling, also suppressing immune surveillance via the regulation of T cell and natural killer cell functions." (PMID 35884546, 2022). "Galectin-3 (Gal-3), a member of soluble β-galactoside-binding lectin families, has been implicated as a key regulator in various inflammation conditions in addition to its well-documented roles in cancer." (PMID 34109213, 2021). "Galectin-3 (gal-3), a member of the galectin family, contains two domains, namely, the C-terminal carbohydrate recognition domain and the N-terminal domain, and is associated with a variety of diseases including cancer, inflammatory diseases, and DM." (PMID 33506012, 2021). "Our results shed light on the significant association of elevated galectin-3 expression with reduced OS or DFS/RFS/PFS in overall cancer patients (pooled HR = 1.79, 95% CI 1.42–2.27, I2= 67.3%, p < 0.01; pooled HR = 1.57, 95% CI 1.04–2.37, I2= 67.1%, p = 0.001)." (PMID 30410421, 2018). "The aberrant expression of galectin-3 in normal thyroid cells, in fact, blocks the apoptotic program, allowing accumulation of DNA mutations and molecular alterations, which in turn promote the development of cancer." (PMID 29393868, 2018). "Galectin-3 has been proven to be associated with the metastasis and invasion of various cancers." (PMID 29254179, 2017). "CLU, NDRG1, CD166, S100A11 and Galectin-1 were associated with carcinoma and Galectin-3." (PMID 28701735, 2017). "Cancer cell–endothelial interaction mediated by cancer cell-associated TF was also shown to enhance expression of endothelial cell surface-associated galectin-3, resulting in increased adhesion of breast and prostate cancer cells to the endothelium of intact well-differentiated micro-vessels." (PMID 27066458, 2016).
cancer (continued). "Compared to galectin-3-deficient cancers, galectin-3-positive cancers are correlated with the presence of inactive GSK-3β, which might facilitate the Wnt/β-catenin pathway." (PMID 26934444, 2016). "Regarding the anticancer properties of IFN-γ, the implication of PI3K/PTEN/galectin-3/AKT/GSK-3β/SHP2 signaling might reflect a strategy hijacked by cancer cells to cause cellular unresponsiveness to IFN-γ." (PMID 26934444, 2016). "Galectin-1 and galectin-3 are expressed by virtually all immune cell lineages, including monocytes, macrophages, T cells, NK cells, B cells, and dendritic cells, and have also been implicated in cancer immunology." (PMID 26589797, 2016). "Importantly, elevated Galectin-3 levels are associated with numerous types of cancer, and frequently correlate with poor outcome." (PMID 25869099, 2015). "In addition, cancer cell-associated T antigens can induce Galectin-3 expression on the endothelium, which enabled cancer-endothelium adhesion." (PMID 24592356, 2014). "Evaluating the usefulness of β-galactoside binding galectin-3 as a diagnostic marker for this type of cancer could open avenues for preventive and therapeutic strategies by employing specific inhibitors of the lectin." (PMID 21958686, 2011). "Intracellular galectin-3 is an apoptosis inhibitor and mRNA splicing promoter whilst cell surface-associated extracellular galectin-3 acts as an adhesion molecule in cell-cell interactions and promotes cancer progression and metastasis." (PMID 20565834, 2010). "Furthermore, a loss of allelic heterozygosity in a specific cancer-related chromosomal region was demonstrated in some HT harbouring galectin-3-positive follicular cells, by using laser capture microdissection." (PMID 15292926, 2004). "In particular, galectin-3 has remained the central protein in the midst of inhibitor discovery, as its overexpression has been associated with cancer drug resistance, and hence it has been identified as a valuable therapeutic target in the fight against cancers." (PMID 34619151, 2021). "Galectin-3 (Gal-3), which is a member of lectins protein able to bind galactose-containing glycoproteins on the cell surface and in the extracellular matrix, has been found to be implicated in various types of disease such as fibrosis, inflammation, and cancer." (PMID 31337151, 2019). "Galectin-3 is widely expressed in intracellular and extracellular spaces and it is a member of the family of carbohydrate-binding proteins associated with cell attachment, angiogenesis, cell proliferation and inhibition of apoptosis, which promotes cancer progression and metastasis." (PMID 29348846, 2017). "It has been shown previously that cell surface-associated galectin-3 acts as a cell adhesion molecule and increases cancer cell homotypic aggregation by interaction with TF antigen expressed by unknown cell surface molecules on adjacent cells under anchorage independent conditions." (PMID 20565834, 2010). "Galectin-3 (Gal3) is one of the most pro-inflammatory proteins and a biomarker of inflammatory diseases and cancer." (PMID 41676549, 2026). "exo-PGPs bound plant lectinsmore rapidly and with higher avidity, whereas endo-PGPs showed greater selectivity toward human galectin-3, strongerinhibition of cholera toxin, and enhanced uptake into 4T1 triple-negativebreast cancer cells." (PMID 41019107, 2025). "As a multi-functional molecule, galectin-3 promotes a range of steps in cancer development, progression, and metastasis, intracellularly and extracellularly." (PMID 41023585, 2025). "Galectin-3 ablation has been shown to downregulate human telomerase reverse transcriptase (hTERT), a pivotal enzyme required for telomere maintenance and cancer cell immortality." (PMID 40710343, 2025). "To investigate the molecular effects associated with LGALS3 loss, we analyzed a consensus gene expression profile generated from CRISPR-Cas9-mediated deletion of LGALS3 across multiple cancer cell lines." (PMID 41153387, 2025).
cancer (continued). "Galectin-3 (Gal-3) is a β-galactoside-binding lectin highly expressed in the TME of invasive cancers." (PMID 39941004, 2025). "Due to its broad involvement in promotion of almost all cancer hallmarks and its profound impact on cancer progression, metastasis and immune modulation, galectin-3 is now widely regarded as a very promising therapeutic target for cancer treatment." (PMID 41023585, 2025). "Inside the cell, galectin-3 typically acts as an anti-apoptotic molecule, helping cells resist programmed cell death and supporting cancer cell survival." (PMID 40333130, 2025). "This study aimed to systematically investigate the transcriptomic impact of LGALS3 deletion and assess its clinical significance in cancer." (PMID 41153387, 2025). "Future work will focus on the isolation and characterization of WCCPSs to better understand their biological effects, particularly their interaction with cancer-related receptors such as galectin-3, and other possible receptors." (PMID 40284312, 2025). "The suppression of the expression of GA-upregulated cancer proteins, including enolase-2, capping protein CapG, galectin-3, and cathepsin D, was observed after p70S6K1 downregulation/blockade." (PMID 40149589, 2025). "These novel, non-carbohydrate galectin-3 inhibitor compounds offer great promise and potential to be developed as galectin-3 targeted therapeutic drugs for cancer treatment." (PMID 41023585, 2025). "This suggests that K2 and L2 can effectively inhibit galectin-3-mediated actions in cancer promotion." (PMID 41023585, 2025). "With increased realization of galectin-3 multi-mode actions in promotion of cancer development, progression and metastasis, there has been an exponential level of recent interest in the development of galectin-3-targeted therapeutics." (PMID 41023585, 2025). "These suggest that K2 and L2 are capable to effectively inhibit a range of galectin-3-mediated activities in cancer progression and metastasis." (PMID 41023585, 2025). "Several natural polysaccharides, glyco-peptides, and carbohydrate-compounds conjugates have been reported as galectin-3 inhibitors in the past few years and show to inhibit galectin-3-mediated actions in cancer." (PMID 41023585, 2025). "Despite higher presence of immune cells, these cancers demonstrated activation of immunosuppressive pathways involving CD44 and galectin-3 that are frequently seen in ICI-resistant cancers." (PMID 41374966, 2025). "Physiologically, increased Galectin-3 is highly relevant to the pathogenesis of a wide range of human diseases, including cancer, fibrosis, and chronic inflammation." (PMID 41194217, 2025). "These suggest that galectin-3 conformation changes in response to binding of these compounds contribute to their inhibitory effect on galectin-3-mediated activities in cancer and immune cells." (PMID 41023585, 2025). "LGALS3 knockout in YAPC cells recapitulated the pan-cancer findings, linking LGALS3 to cell morphogenesis and proliferation." (PMID 41153387, 2025). "The galactoside-binding galectin-3 is a multi-mode promoter in a broad range of cancers, as well as in the pathogenesis of inflammation and fibrosis-associated diseases." (PMID 41023585, 2025). "Galectin-3 undergoes notable context-dependent reprogramming that links chronic inflammation to cancer development." (PMID 40806347, 2025). "BCAP31, recognised as a prognostic factor across various cancers, supports angiogenesis via galectin-3 upregulation." (PMID 40427675, 2025). "To do so, we used TD-139, a thiodigalactoside small-molecule inhibitor that targets the Galectin-3 carbohydrate-binding domain and is currently being evaluated in clinical studies for its therapeutic potential in fibrotic, cancer and inflammatory disorders." (PMID 40161708, 2025). "These non-carbohydrate compounds, therefore, represent a novel class of galectin-3 inhibitors and offer great potential to be developed as galectin-3-targeted therapeutic drugs for cancer treatment." (PMID 41023585, 2025).
cancer (continued). "Galectin-3 mediates cancer progression and metastasis, as it is involved in various cancer cell activities, including growth, transformation, apoptosis, angiogenesis, adhesion, invasion, and metastasis." (PMID 40284554, 2025). "Together, the modular analysis based on LGALS3 deletion revealed discrete gene networks involved in cell division, stress adaptation, and signaling processes that are shared among multiple cancer cell models." (PMID 41153387, 2025). "Overexpression of galectin-3 is a common feature in cancers of all major types such as breast, prostate, colorectal and lung cancers." (PMID 41023585, 2025). "Studies have shown that cancer cells expressing galectin-3 exhibit stem cell-like behavior, can escape apoptosis, and have features such as T cell inactivation." (PMID 39451592, 2024). "In this study, an initial pan-cancer analysis was conducted to investigate the expression and prognosis of LGALS3." (PMID 38643145, 2024). "A multi-omic screening then identifies leukemia inhibitory factor (LIF) and galectin-3 (Gal3) as the key cytokines released by these cancer cell types to trigger brain activation." (PMID 38467743, 2024). "TNF-α can also activate the expression of T-cell immunoglobulin mucin-3 (TIM-3), allowing cancer cell-expressed Galectin-3 (Gal-3) to block T cells by binding to TIM-3 on the T cell membrane." (PMID 39101140, 2024). "An immune-suppressor that has gained interest in cancer research is Galectin-3, a mammalian lectin with affinity for β-galactoside-containing glycoconjugates." (PMID 39759523, 2024). "This work began with a pan-cancer study of LGALS3 expression and its predictive value in a variety of human malignancies." (PMID 38643145, 2024). "Galectin‐3 (Gal‐3) is closely related to microglial activation in the nervous system and can promote the aggregation of cancer cells in tumors." (PMID 39592913, 2024). "LGALS3 has been reported to be highly expressed in various cancers, and negatively correlated with the prognosis of HCC patients." (PMID 39795978, 2024). "It is noteworthy that Galectin 9 (Gal-9) and galectin 3 (Gal-3) can interact with PD-1 and thus are emerging targets for cancer immunotherapy in different combinations." (PMID 39507530, 2024). "galectin-3, which is expressed in cancer cells, is a soluble ligand that binds to NKp30 and inhibits NKp30-mediated activation and cytolysis." (PMID 39408655, 2024). "Nevertheless, antiapoptotic galectin-3 function is consistent with its known anti-apoptotic role in other cell types, including cancer cells." (PMID 38990375, 2024). "For all these reasons Galectin-3 has been extensively studied in many different types of cancers, affecting various human tissues." (PMID 39685748, 2024). "Namely, the T-antigen has been described as promoting metastasis by facilitating cancer cell interaction with soluble galectins, particularly galectin-3 (Gal-3)." (PMID 38612533, 2024). "Fig. (4B) shows that Galectin-3 and Calcitonin are the cluster labels of cluster 0 and cluster 1, respectively, both of which are closely related to the diagnosis and treatment of cancer." (PMID 37608676, 2024). "For the investigation of LGALS3’s potential functions in carcinogenesis, TIMER2 was utilized to explore LGALS3 expression among different cancer types of TCGA (The Cancer Genome Atlas)." (PMID 38643145, 2024). "Next, the prognostic value of LGALS3 expression in the 23 kinds of cancer patients was then determined." (PMID 38643145, 2024). "For example, there is promise in utilizing revacept to inhibit the interaction between platelet collagen receptors (particularly GPVI) and galectin-3 in cancer cells." (PMID 39764464, 2024). "To elucidate if LGALS3 is associated with the EMT in other model systems and under different conditions, we referred to our TGF-β1 treated OVCA420 cancer cells and correlated expression of LGALS3 with the cancer specific EMT signature scores." (PMID 38086828, 2023).